SRSF1 (serine and arginine rich splicing factor 1)
Description:
Plays a role in preventing exon skipping, ensuring the accuracy of splicing and regulating alternative splicing. Interacts with other spliceosomal components, via the RS domains, to form a bridge between the 5'- and 3'-splice site binding components, U1 snRNP and U2AF. Can stimulate binding of U1 snRNP to a 5'-splice site-containing pre-mRNA. Binds to purine-rich RNA sequences, either the octamer, 5'-RGAAGAAC-3' (r=A or G) or the decamers, AGGACAGAGC/AGGACGAAGC. Binds preferentially to the 5'-CGAGGCG-3' motif in vitro. Three copies of the octamer constitute a powerful splicing enhancer in vitro, the ASF/SF2 splicing enhancer (ASE) which can specifically activate ASE-dependent splicing. Isoform ASF-2 and isoform ASF-3 act as splicing repressors. May function as export adapter involved in mRNA nuclear export through the TAP/NXF1 pathway.
Synonyms: ASF; SF2; SF2P33; SFRS1; SRp30a; MGC5228; NEDFBA
Tractability: Small molecule: a structure with a bound ligand is known. PROTAC: UniProt records ubiquitination sites on it; ubiquitination databases record sites on it; its protein half-life has been measured.
Gene: Protein-coding gene on chromosome 17 (58,000,919 to 58,007,346, reverse strand). Ensembl gene ENSG00000136450.
Subcellular location: Chromosome; Cytoplasm; Nucleus speckle
Subcellular location (Human Protein Atlas): Nucleoplasm; Cytosol
Pathways (Reactome):
Metabolism of RNA: Processing of Capped Intron-Containing Pre-mRNA; Transport of Mature mRNA derived from an Intron-Containing Transcript; mRNA 3'-end processing; mRNA Polyadenylation; mRNA Splicing - Major Pathway; mRNA Splicing - Minor Pathway
Disease: Dengue Virus-Host Interactions
Gene Ontology:
Molecular function: DNA topoisomerase binding; mRNA binding; protein binding; RNA binding; nucleic acid binding; RS domain binding
Biological process: alternative mRNA splicing, via spliceosome; mRNA 5'-splice site recognition; positive regulation of lipid biosynthetic process; positive regulation of RNA splicing; mRNA processing; mRNA splice site recognition; mRNA splicing, via spliceosome; regulation of alternative mRNA splicing, via spliceosome; regulation of RNA splicing; cellular response to interleukin-17; interleukin-17-mediated signaling pathway; mRNA stabilization; protein localization to nucleus; protein localization to P-body
Cellular component: catalytic step 2 spliceosome; chromatin; cytoplasm; cytosol; exon-exon junction complex; nuclear speck; nucleoplasm; nucleus; chromosome
Genetic constraint (gnomAD): Loss-of-function variants: 1 observed, 27.86 expected, observed/expected ratio (o/e) 0.0359, 90% interval 0.012 to 0.17. The upper end of that interval is the gene's LOEUF score, 0.17, which puts it in group 1 of 6, group 1 being the genes least tolerant of losing a copy. Missense variants: 65 observed, 376.34 expected, observed/expected ratio (o/e) 0.17, 90% interval 0.14 to 0.21. Synonymous variants: 132 observed, 134.48 expected, observed/expected ratio (o/e) 0.98, 90% interval 0.85 to 1.13.
Homologues: Orthologues: mouse Srsf1 (100% identical), chimpanzee SRSF1 (99% identical), dog SRSF1 (99% identical), guinea pig SRSF1 (99% identical), pig SRSF1 (99% identical), rat Srsf1 (99% identical), tropical clawed frog srsf1 (99% identical), zebrafish srsf1b (96% identical), zebrafish srsf1a (95% identical). Paralogues in human: SRSF9 (65% identical), SRSF6 (47% identical), SRSF4 (46% identical), SRSF5 (42% identical), SRSF7 (37% identical), SRSF3 (31% identical), RSRC2 (21% identical), RSRP1 (19% identical).
Diseases named in the same sentence as SRSF1 in open-access papers:
SRSF1 is named in the same sentence as 168 diseases in open-access papers, as found by Europe PMC text mining. Sharing a sentence is not in itself a finding about the gene and the disease. The quoted sentences say what the papers report.
breast carcinoma (86 papers, 2008 to 2025). "Among the SR protein members, SRSF1 (also known as ASF/SF2) was the first identified and has been implicated in the development and progression of glioma, breast cancer, lung cancer and other tumor types by regulating gene splicing." (PMID 39578852, 2024). "We also identified SRSF1, an RNA-binding protein strongly linked with breast cancer progression and metastasis, to be upregulated in DAB2IP-low Luminal A tumors." (PMID 39418101, 2024). "It has been confirmed that SRSF1 expression is positively associated with breast cancer grade and acts as an indicator of poor prognosis." (PMID 37097746, 2023). "For example, SRSF1 has been shown to be increased in breast cancer; SRSF1 is associated with an increase in the Bcl-xL/Bcl-xS ratio." (PMID 31552099, 2019). "To explore the mechanism by which PRMT5 regulates splicing in BCSCs, we focused on the RNA-binding protein SRSF1 because of its association with breast cancer, its ability to regulate cisplatin sensitivity, and that PRMT5-dependent methylation regulates splicing in AML cells." (PMID 39695328, 2025). "CircRPAP2, a circRNA derived from the host gene RPAP2, is expressed in breast cancer tissues and inhibits the proliferation and migration of breast cancer by competing with the association between the splicing factors SRSF1 and PTK2 pre-mRNA to modify the alternative splicing pattern of PTK2 mRNA." (PMID 35884948, 2022). "Moreover, the activation of oncogenes can lead to the malignant progression of cancer, as the high expression of SRSF1 in breast cancer is positively associated with a higher tumor grade." (PMID 35971121, 2022). "Moreover, the amplification of the chromosome 17q23 and chromosome 6p21 regions has been shown to cause the overexpression of SRSF1 in breast cancer and SRSF3 in lung and cervical carcinoma, respectively." (PMID 32596243, 2020). "The overexpression of SRSF1 was also shown to increase cell proliferation through the production of the exon 5 lacking-variant cyclin D1b in prostate cancer and to induce epithelial mesenchymal transition by stimulating the production of the ΔRon variant in breast cancer." (PMID 32596243, 2020). "In addition, the up-regulated SRSF1 expression with a concomitant increase in the relative level of exon-9-included cancer susceptibility candidate 4 (CASC4) transcripts was revealed in breast cancer cells compared to the normal ductal cells." (PMID 27983653, 2016). "Our findings supported the anti-tumor effects of CYT against drug resistant breast cancer and identified SRSF1 as a novel molecular mechanism." (PMID 40176901, 2025). "In this study, through transcriptome sequencing analysis, we found that the SRSF1 level in breast cancer resistant cells was significantly reduced after receiving CYT treatment, and the cellular experiments verified this finding." (PMID 40176901, 2025). "For example, SRSF1 is upregulated in lung, pancreatic, brain, and breast cancers, promoting isoform switching that drives tumor growth." (PMID 39885614, 2025). "In this study, we identified the effects of CYT on overcoming drug resistance of breast cancer and identified the potential regulatory with SRSF1/MYO1B axis via transcriptome analysis and experiment verification." (PMID 40176901, 2025). "While previous research has shown that SRSF1 overexpression is associated with increased malignancy and drug resistance in breast cancer, our results demonstrate that CYT treatment significantly reduces SRSF1 expression in drug-resistant cells." (PMID 40176901, 2025). "For example, PRMT1 overexpression is associated with increased arginine methylation and aberrant exon inclusion of SRSF1, which is essential for breast cancer cell growth; PRMT1 suppresses the anti-tumor immune response via arginine methylation of cGAS." (PMID 40744915, 2025).
breast carcinoma (continued). "SRSF1 promoted the proliferation and migration of breast cancer cells and inhibited the apoptosis of breast cancer cells via regulating the alternative splicing of PTPMT1." (PMID 40176901, 2025). "Srsf3 KO was found to reduce Srsf1 protein expression both from the Erbb2 breast cancer and DEN-induced liver cancer." (PMID 40568073, 2025). "In clinical breast cancer samples, the expression of SRSF1 was upregulated and positively correlated with tumor grade, Ki-67 expression and poor prognosis." (PMID 40176901, 2025). "In breast cancer tissues, high expression of SRSF1 (sometimes referred to as SF2/ASF) represents a significant unfavorable prognostic predictor." (PMID 40129567, 2025). "Knockdown of SRSF1 can reduce the expression level of full-length MYO1B protein in both drug-resistant and parental breast cancer cells, indicating that SRSF1 regulated the alternative splicing of MYO1B in breast cancer cells." (PMID 40176901, 2025). "SRSF1 also exerts oncogenic roles in breast cancer partially by regulating apoptosis and cell proliferation, and is correlated with tumor grade and poor prognosis." (PMID 38735973, 2024). "Next, to investigate the effect of loss of DAB2IP on NF-κB target genes, we selected SRSF1, and BIRC5, which are known to play important protumorigenic roles in breast cancer." (PMID 39418101, 2024). "Numerous studies have investigated the role of SRSF1 in tumorigenesis, with a focus on its involvement in transcriptional regulation mediated by lncRNA or microRNA in breast cancer, liver cancer, and lung cancers." (PMID 38735973, 2024). "Among these, the splicing factor SRSF1 is noted for its involvement in numerous AS events in breast cancer." (PMID 38723164, 2024). "For example, the generation of oncogenic isoforms of SRSF1, SRSF3, SRSF6, and TRA2B have been associated with lung cancer, breast cancer, and colon cancer." (PMID 38778254, 2024). "Its splicing is probably regulated by SRPK1 and SR family splicing factors, including SRSF1, which is frequently overexpressed in breast cancer." (PMID 37296881, 2023). "Overexpression of SRSF1 can induce tumor formation in epithelial cells and inhibit apoptosis of breast cancer cells." (PMID 36611187, 2023). "A similar observation was reported in breast cancer, where transcriptional upregulation of several spliceosome components, including SRSF1, resulted in MYC hyperactivation and oncogenic translation impacting critical SF networks." (PMID 36535935, 2022). "SRSF1, which is upregulated in breast cancer, induces SRSF1-regulated alternative splicing events, such as exon inclusion and skipping, by binding to the 5′ or 3′ splice site." (PMID 36142830, 2022). "SRSF-1 was expressed in breast cancer cells with a p-eGFP-C1 vector (EGFP-SRSF-1), which has been shown previously to be highly homologous with endogenous SRSF-1 localization and function." (PMID 36096767, 2022). "SRSF1 is consistently overexpressed in breast cancer samples and positively correlates with tumor grade and poor prognosis." (PMID 35711821, 2022). "For example, highly expressed SRSF1 in breast cancer promotes cancer progression via the oncogenic splicing switch of PTPMT1." (PMID 36140826, 2022). "Positive correlations between MYC and SRSF1 expression have been reported across different malignant contexts, including lung and breast cancers." (PMID 36140826, 2022). "Some SR proteins are overexpressed in cells and act as oncoproteins; for example, SRSF1 is upregulated in lung, colon, and breast cancers and its overexpression induces immortalization of mouse fibroblasts and human and mouse mammary epithelial cells." (PMID 33923658, 2021). "Cyclin D1a contains all the 5 exons but Cyclin D1b formed by intron 4 inclusion and exon 5 skipping which is modulated by Serine and arginine rich splicing factor 1 (SRSF1) for up-regulation of Cyclin D1b in breast cancer." (PMID 33438725, 2021).
breast carcinoma (continued). "In breast cancer, SRSF1 regulates the alternative splicing of the pro-apoptotic gene BIM, which increases the expression of splice variant lacking the BH3 domain, thereby inhibiting apoptosis." (PMID 32760211, 2020). "In breast cancer, a member of SR proteins, SRSF1, has been shown to regulate various alternative splicing events of cancer-related genes and promote cancer progression." (PMID 32106418, 2020). "In this investigation, it is highlighted that SRSF1 in cooperation with MYC is involved in breast cancer progression." (PMID 32099613, 2019). "SRSF1 is amplified and upregulated in breast cancer and transforms immortal cells when overexpressed." (PMID 31666932, 2019). "The oncoprotein splicing factor SRSF1, is amplified in breast cancer and is a potential target for cancer therapy." (PMID 30962446, 2019). "For example, up-regulated expression of the SRSF1 protein induced a relatively high level of the BIM+exon 3 isoform in breast cancer cells." (PMID 27983653, 2016). "SRSF1 is frequently upregulated in breast cancers and its overexpression leads to the formation of larger acinar cells, due to increased proliferation and delayed apoptosis during acinar morphogenesis." (PMID 26405162, 2015). "SRSF1 is located on chromosome 17 and is a commonly amplified region in breast cancer, correlating with poor prognosis." (PMID 25845590, 2015). "Knockout of the serine/arginine-rich (SR)-related protein Pinin (Pnn) leads to early embryonic lethality, and its knockdown in breast cancer cells leads to apoptosis due to reduced expression of SRSF1 and increased expression of Bim." (PMID 26405162, 2015). "Analysis of the SRSF1 gene on the cBio Cancer Genomics Portal shows amplification of SRSF1 mainly in breast cancers." (PMID 23935626, 2013). "With relevance to breast cancer progression, alternative splicing events mediated by SRSF1 are capable of promoting mammary gland tumorigenesis." (PMID 23284704, 2012). "The involvement of SRSF1 in the production of the anti-apoptotic of Mcl-1 in breast cancer cells adds to the number of cancer specific splicing events controlled by this SR protein." (PMID 23284704, 2012). "Regulation of Mcl-1 by SRSF1 and 5 was also investigated in a second breast cancer cell line using MDA-MB-231 cells, described as having an invasive phenotype in vitro." (PMID 23284704, 2012). "Knockdown of SRSF1 resulted in a decrease in Mcl-1 in the breast cancer cell lines studied and an increase in the choriocarcinoma cells, and achieved this by both affecting protein stability and translation of Mcl-1." (PMID 23284704, 2012). "Targeting SRSF1 or MYO1B may be identified as a novel molecular mechanism to against drug resistant in breast cancer." (PMID 40176901, 2025). "To determine whether SRSF1 is involved in the inhibitory effect of CYT on breast cancer cells by affecting alternative splicing, we examined several representative target genes." (PMID 40176901, 2025). "Given that SRSF1 has been linked to breast cancer and is methylated by PRMT5, we posited that SRSF1 may be one RBP that is methylated by PRMT5 contributing to splicing fidelity in BCSCs." (PMID 39695328, 2025). "Splicing factor SRSF1 affects the isoform switching of many genes in breast cancer cells." (PMID 40425760, 2025). "SRSF1 plays a role in regulating alternative splicing in breast cancer cells." (PMID 40176901, 2025). "Studies have proved that high expression of splicing factor SRSF1 can promote the occurrence and development of lung cancer, breast cancer, pancreatitis, and other diseases and cancers, indicating that SRSF1 is a key protein in the regulation of cancer cell expression." (PMID 39330852, 2024).
breast carcinoma (continued). "In contrast, in breast cancer, overexpressed SRSF1, through its function in constitutive and alternative splicing, increases BIN1 isoforms that lack pro-apoptotic functions, thereby causing BIN1 failed interaction with MYC, and leading to MYC-induced epithelial cell transformation." (PMID 38778254, 2024). "Thus, SRSF1 overexpression is observed in 13% of patients with breast cancer, 25% with colon cancer, and 25% with lung cancer." (PMID 36732501, 2023). "Moreover, in breast cancer, SRSF1 moves to the cytoplasm where it promotes the translation of MYC and other mRNAs." (PMID 36732501, 2023). "Thus, to our knowledge, this is the first study demonstrating an IGF-1 induced localization of SRSF-1 in breast cancer and its ability to regulate FASN expression." (PMID 36096767, 2022). "In addition, the identification of the circRPAP2/SRSF1/PTK2 axis provides new insights into the pathogenesis of breast cancer and highlights a novel target for the development of oncotherapeutics." (PMID 35368030, 2022). "Interestingly, SRSF1 has been shown to regulate alternative splicing events, especially in breast cancer and lung cancer." (PMID 34768829, 2021). "In addition, colony formation assay revealed that overexpression of NSrp70 significantly reduced colony formation in E0771 breast cancer cells, whereas SRSF1 increased it." (PMID 34037780, 2021). "Out-of-control AS events regulated by SRSF1 can encourage the formation of breast cancer." (PMID 32079071, 2020). "Since the upregulation of CCND1b was also observed in breast cancer, SRSF1 may regulate CCND1b expression in the similar manner in breast and prostate cancers." (PMID 32106418, 2020). "Additionally, the oncogenic SRSF1 and SRSF3 are overexpressed in multiple human cancers, including lung, colon, and breast cancers, despite limited mutations of them have been revealed." (PMID 31065692, 2019). "A recent study has indicated that SRSF1 could promote the splicing of CD44V6 (V6 exon-containing isoform) splicing in breast cancer cells." (PMID 31857793, 2019). "There is increasing evidence that spliceosomal component genes themselves are dysregulated in breast cancer, through mutations in SF3B1 that are also observed in metastatic disease and upregulation of SF3B3 and SRSF1 in particular, which are associated with resistance to endocrine therapy." (PMID 29848666, 2018). "Experiments support an important function for SRSF1 protein in breast cancer cells." (PMID 23935626, 2013). "Notably, the inhibitor of PRMT1 (iPRMT1) was able to inhibit breast cancer cell growth, and the iPRMT1 was even more effective when combined with inhibitors targeting SRSF1 phosphorylation (SPHINX31 and SRPIN340), suggesting the potential value of combination therapy." (PMID 40129567, 2025). "Thus, the development of small-molecule inhibitors or modulators targeting SRSF1 or MYO1B may provide a novel therapeutic strategy for drug-resistant breast cancer." (PMID 40176901, 2025). "In addition, the expression levels of SRSF1 protein and RNA in drug-resistant breast cancer cells were significantly increased compared with parental cells, suggesting the SRSF1 may be the target of CYT in overcoming drug resistance." (PMID 40176901, 2025). "Supporting a global reshape of cancer-related splicing profiles in metastatic breast cancer we found an enrichment of RNA-binding motifs recognized by several splicing regulators, which have aberrant expression levels or activity during breast cancer progression, including SRSF1." (PMID 33918758, 2021). "However, the profile of SRSF1-regulated AS events in MCF7 breast cancer cells and the direct regulatory mechanism remain unclear." (PMID 33992102, 2021). "Moreover, they support the conclusion that SRSF1 activation could contribute to the malignant progression of breast cancers by stabilizing DCUN1D5 expression through the involvement of the AS-NMD pathway." (PMID 33918758, 2021).